RIPK2 (receptor interacting serine/threonine kinase 2)
Diseases named in the same sentence as RIPK2 in open-access papers (continued):
Sharing a sentence is not in itself a finding about the gene and the disease.
gastric cancer (11 papers, 2020 to 2026). A primary or metastatic malignant neoplasm involving the stomach. "It has also been reported that RIPK2 polymorphisms are related to tumor infiltration degree, lymph node metastasis and survival in urothelial bladder cancer and susceptibility to gastric cancer." (PMID 35477477, 2022). "Only one study has suggested that the carriers of RIPK2 single nucleotide polymorphism rs16900627 minor allele may have a higher risk for the progression of gastric cancer." (PMID 33633788, 2021). "Junquan Song conducted bioinformatics analysis across 33 different types of cancer, including gastric cancer, and reported that receptor-interacting protein kinase 2 (RIPK2) plays a key role." (PMID 39309860, 2024). "In gastric cancer, downregulation of RIPK2 inhibits the growth, apoptosis and migration of gastric cancer cells by inhibiting the NF-κB signalling pathway." (PMID 35473583, 2022). "For instance, RIPK2 had been previously reported to play an important role in modulating gastric cancer (GC) cell proliferation, migration, and apoptosis through the NF-κB signaling pathway." (PMID 36193316, 2022). "RIPK2 is also involved in the regulation of gastric cancer tumor growth by inhibiting apoptosis." (PMID 41563982, 2026). "An increase in the expression of RIPK2 facilitates resistance to innate and adaptive immune therapeutic techniques via pathways such as the IL-6/JAK/STAT3 signaling pathway, the interferon-γ response, and the interferon-α response; thus, RIPK2 plays an important role in gastric cancer." (PMID 39309860, 2024). "RIPK2 contributes to both proliferation and invasion in cancers such as ovarian and gastric cancers, mediates NOD1 to regulate the NF-κB pathway, and promotes immunotherapy resistance by triggering cytotoxic T lymphocyte dysfunction, which is highly detrimental to prognosis." (PMID 37031243, 2023). "It was previously demonstrated that RIPK2 might play a role in promoting malignant tumor progression; however, the precise function of RIPK2 in the onset and progression of gastric cancer (GC) remains unclear." (PMID 33633788, 2021).
colorectal cancer (10 papers, 2018 to 2025). A primary or metastatic malignant neoplasm that affects the colon or rectum. "ASAP1 and RIPK2 were reported as hub proteins of inflammatory bowel disease and colorectal cancer; and ASAP1 expression might be associated with pulmonary and bladder neoplasms." (PMID 35477477, 2022). "In colorectal cancer, the mRNA expression level of RIPK2 is related to some proteins involved in cancer occurrence, and patients with higher expression of RIPK2 also have higher expression of vascular endothelial growth factor (VEGF)." (PMID 35473583, 2022). "Our previous study demonstrated that RIPK2 was overexpressed in colorectal cancer (CRC), and, in combination with Fusobacterium nucleatum, was involved in the regulation of CRC metastases." (PMID 33633788, 2021). "Two important study demonstrated that Fusobacterium nucleatum, a well-recognized proinflammatory bacterium, can facilitate ulcerative colitis and promote colorectal cancer metastasis via upregulation of RIPK2 expression." (PMID 33633788, 2021). "Our previous research indicated that RIPK2 facilitated the colorectal cancer cells migration and invasion via inducing epithelial-mesenchymal transition." (PMID 33633788, 2021). "Inhibition of RIPK2 can prevent the production of tumorigenic IL-17 in colorectal cancer." (PMID 37016317, 2023). "In addition, the expression of RIPK2 is positively correlated with IL-6, IL-8 and VEGF, which play a role in colorectal cancer, indicating that RIPK2 may be involved in the occurrence of colorectal cancer and that the expression level of RIPK2 is correlated with the prognosis of colorectal cancer." (PMID 35473583, 2022). "Although the role of RIPK2 in cancer development has been investigated, especially in colorectal cancer, its function in GC is not yet clear." (PMID 33633788, 2021). "RIPK2 was also shown to play different roles in different cancer types; however, in colorectal cancer (CRC), its role is not well established." (PMID 34356990, 2021).
inflammatory bowel disease (10 papers, 2015 to 2025). A spectrum of small and large bowel inflammatory diseases of unknown etiology. "We have observed correlations between RIPK2 activation, AMPK loss and YAP proliferation in inflammatory bowel disease patients to suggest a link between key elements involved in ImmunoMET oncogenesis." (PMID 40095546, 2025). "Previous studies have shown that RIPK2 might be responsible for the chronic inflammation of inflammatory bowel disease (IBD), and the high level of RIPK2 expression was associated with advanced tumors and metastasis of inflammatory breast cancer." (PMID 35477477, 2022). "Thus, target treatment on RIPK2 showed an ideal control of inflammatory diseases, such as cystic fibrosis, asthma, inflammatory bowel disease and pancreatitis." (PMID 35907206, 2022). "The dynamics associated with these hotspots are crucial for the interaction between RIPK2 and XIAP, a key element in NOD1/2-mediated immune responses, with implications in inflammatory bowel disease and other conditions." (PMID 39190764, 2024).
inflammatory breast carcinoma (9 papers, 2018 to 2025). An advanced, invasive breast adenocarcinoma characterized by the presence of distinct changes in the overlying skin. "In addition, increased RIPK2 activity contributing to inflammatory breast cancer pathogenesis and aggressiveness." (PMID 33633788, 2021). "In addition, RIPK2 played a crucial role in the formation and progression of oral squamous cell cancer, inflammatory breast cancer." (PMID 33633788, 2021). "In inflammatory breast cancer (IBC), RIPK2 hyperactivation has been documented, with elevated RIPK2 and NF-κB levels observed in IBC patients even before chemotherapy." (PMID 40406369, 2025).
leprosy (9 papers, 2010 to 2024). Leprosy is a chronic infectious disease affecting primarily the skin and peripheral nervous system. "The most highly differentiated variant in the RIPK2 gene shows an increase in frequency after the Black Death of an allele protective against leprosy." (PMID 38232165, 2024). "The RIPK2 allele previously shown to be protective against leprosy showed increased allele frequency after the Black Death." (PMID 38232165, 2024). "In addition, RIPK2 haplotype GA was observed more frequently in paucibacillary (PB) patients in comparison to controls inferring an increased risk of leprosy (OR = 1.8, 95% CI = 1.1–2.8, P = 0.018)." (PMID 24015287, 2013). "NOD2 interacts with the adaptor protein kinase RIPK2 for signaling, and mutations in both NOD2 and RIPK2 have been associated with leprosy and/or its endophenotypes." (PMID 37262021, 2023). "Reports have linked NOD2 to LRRK2-dependent intestinal homeostasis and RIPK2 phosphorylation, and LRRK2 polymorphisms are also associated with Crohn’s disease and leprosy susceptibility, indicating a common genetic network at play." (PMID 37262021, 2023). "NOD2 and RIPK2 mRNA were found to be up-regulated 3- to 4-fold in skin tissue samples from people with leprosy compared to controls, and the frequency of NOD2-positive cells was 3 times higher in tuberculoid than in lepromatous lesions." (PMID 37262021, 2023). "In a family-based Vietnamese sample, 16 significant GWAS SNPs were tested for association and SNPs tagging HLA-DR–DQ, RIPK2, NOD2 and CCDC122–LACC1 were validated as risk factors for leprosy susceptibility." (PMID 30116885, 2018). "In total, 15 SNPs located in five loci—HLA-DR–DQ, RIPK2, TNFSF15, NOD2 and CCDC122-LACC1—were significantly associated with leprosy (p < 1.00 × 10−10)." (PMID 30116885, 2018). "A recent genome wide study in Chinese leprosy patients has provided vital insights on the role of NOD2 (rs9302752A/G), LRRK2 (rs1873613A/G) and RIPK2 (rs40457A/G and rs42490G/A) variants in regulating the leprosy infection." (PMID 24015287, 2013). "Distribution of investigated RIPK2 haplotypes in clinically classified leprosy patients and controls." (PMID 24015287, 2013). "Distribution of investigated NOD2, RIPK2, and LRRK2 variants in clinically classified leprosy patients and controls." (PMID 24015287, 2013). "In this study, we investigated 211 clinically classified leprosy patients and 230 ethnically matched controls in Indian population by genotyping four variants in NOD2 (rs9302752A/G), LRRK2 (rs1873613A/G), RIPK2 (rs40457A/G and rs42490G/A)." (PMID 24015287, 2013). "Moreover, RIPK2 was validated in an Indian population, while LRRK2 was found to be associated with leprosy and the PB clinical form in Chinese and Indian population samples." (PMID 30116885, 2018). "A stepwise association study of leprosy and the non-HLA genes that were significantly associated in the GWAS (RIPK2, TNFSF15, NOD2 and CCDC122-LACC1) was conducted in four independent Brazilian population samples." (PMID 30116885, 2018). "We investigated the possible association of gene variants NOD2 (rs9302752A/G), LRRK2 (rs1873613A/G) and RIPK2 (rs40457A/G and rs42490G/A) that are vital for NOD2 signalling and subsequent activation of the NF-kB complex in a cohort of clinically classified leprosy patients." (PMID 24015287, 2013). "Thus, the leprosy susceptibility loci, including NOD2, RIPK2, TNFSF15, LACC1, LRRK2, IL12B, and HLA‐DR in phagocytes and IL23R, TYK2, and CSK in T cells, may interfere with the synergistic antimicrobial response between phagocytes and T cells." (PMID 38020709, 2023). "Finally, we cannot exclude the possibility that NOD2, TNFSF15 and RIPK2 are not true leprosy susceptibility loci." (PMID 20617178, 2010).
leprosy (continued). "In a familial sample from Vietnam including 286 MB and 188 PB leprosy patients (WHO-88), signals located in HLA-DR-DQ, RIPK2, CCDC122, LACC1, and NOD2 were validated (p < 0.05), and the effect was stronger in MB patients for HLA-DR-DQ, CCDC122, and LACC1." (PMID 27219008, 2016). "Among the genes specific for CD, RIPK2, LACC1, and NOD2 have been shown to be associated in leprosy studies but not specifically with the PB form (NOD2 and RIPK2 with leprosy per se and LACC1 with MB leprosy)." (PMID 27219008, 2016). "Indeed, while several genes with known overlap of IBD and leprosy were detected (i.e. RIPK2, LACC1 and IL23R), there was no genome-wide statistical enrichment for IBD risk alleles in T1R-free leprosy (p = 0.09)." (PMID 28222097, 2017).
pancreatic cancer (6 papers, 2021 to 2026). "The paired protein kinases PRKCI and RIPK2 promote pancreatic cancer growth and metastasis through activation of the JNK/ERK pathway via NF-κB phosphorylation." (PMID 41563982, 2026). "In osteosarcoma, Prkci promoted cell growth via the Akt/mTOR pathway, while in pancreatic cancer, Prkci and RIPK2 jointly enhanced NF-κB/JNK/ERK signaling, driving cancer cell proliferation and invasion." (PMID 40840329, 2025). "Prkci also contributes to pancreatic cancer growth and metastasis through its interaction with RIPK2." (PMID 40840329, 2025). "Furthermore, previous research has highlighted the role of Prkci in promoting tumor growth and metastasis in pancreatic cancer via its interaction with the kinase RIPK2, leading to increased phosphorylation of NF-κB, JNK, and ERK pathways." (PMID 41188443, 2025). "This analysis showed that the RIPK2 had a higher expression in gastric, breast, esophageal, colorectal, head and neck, liver, kidney, as well as pancreatic cancers, myeloma and sarcoma, compared to that in the respective normal tissues." (PMID 33633788, 2021).
prostate carcinoma (6 papers, 2022 to 2026). A carcinoma that arises from epithelial cells of the prostate gland. "The results showed that RIPK2 expression was upregulated in prostate cancer tissues and was associated with poor pathological grading." (PMID 41563982, 2026). "Receptor-interacting protein kinase 2 (RIPK2) has been shown to play a role in drug resistance in various cancers; however, its role and the underlying mechanism of chemoresistance in prostate cancer are unclear." (PMID 41563982, 2026). "We analyzed data from The Cancer Genome Atlas for RIPK2 expression in prostate cancer and its association with clinicopathological features." (PMID 41563982, 2026). "In prostate cancer, RIPK2 is highly expressed in metastatic cases and has been linked to disease progression and poor prognosis." (PMID 40406369, 2025). "It is suggested that RIPK2 regulates P-gp protein expression in prostate cancer cells through the NF-κB pathway." (PMID 41563982, 2026). "In this study, we aimed to observe the effect of RIPK2 on the chemoresistance of prostate cancer cells and the mediatory role of P-gp to provide a reference for the development of novel therapeutics." (PMID 41563982, 2026). "Taken together, these results suggest that RIPK2 mediates DTX resistance in prostate cancer cells through the NF-κB/P-gp signaling pathway." (PMID 41563982, 2026). "We also elucidated the role and mechanism of action of RIPK2 in prostate cancer cell resistance to docetaxel (DTX)." (PMID 41563982, 2026). "RIPK2 and its downstream signaling molecules are potential targets for the treatment of chemoresistant prostate cancer." (PMID 41563982, 2026). "To explore the biological role of RIPK2 in prostate cancer cells, we examined the NF-κB signaling pathway." (PMID 41563982, 2026). "We first analyzed prostate cancer RIPK2 expression in TCGA database using the University of Alabama at Birmingham cancer data analysis (UALCAN) portal." (PMID 41563982, 2026). "We further validated the role of the RIPK2/NF-κB/P-gp signaling pathway in the resistance of prostate cancer cells to DTX." (PMID 41563982, 2026). "RIPK2 mRNA levels were upregulated in prostate cancer tissues when compared to those in normal prostate tissues." (PMID 41563982, 2026). "Our study revealed a potential mechanism by which RIPK2 regulates the resistance of prostate cancer cells to chemotherapy." (PMID 41563982, 2026). "In conclusion, RIPK2 expression is upregulated in prostate cancer, and its expression correlates with pathological grading." (PMID 41563982, 2026). "Our study found that RIPK2 expression was elevated in 22RV1/DTX, C4-2/DTX, PC-3/DTX, and DU145/DTX prostate cancer cells, and silencing RIPK2 expression increased cell sensitivity to DTX." (PMID 41563982, 2026). "Recent study showed that RIPK2 reduced prostate cancer metastasis through regulating c-Myc stability and activity." (PMID 37016317, 2023). "However, the biological mechanism of action of RIPK2 in prostate cancer is not fully understood and requires further investigation." (PMID 41563982, 2026). "Consistently, RIPK2 expression positively correlated with prostate cancer Gleason scores." (PMID 41563982, 2026). "Additionally, NF-κB inhibition reversed the RIPK2-induced upregulation of P-gp expression in prostate cancer cells." (PMID 41563982, 2026). "This suggests that RIPK2 activates the NF-κB signaling pathway in prostate cancer cells." (PMID 41563982, 2026). "Our TCGA analysis revealed that RIPK2 mRNA levels were upregulated in prostate cancer tissues." (PMID 41563982, 2026). "RIPK2 expression was consistently positively correlated with prostate cancer Gleason scores." (PMID 41563982, 2026). "Thus, we examined the effects of varying RIPK2 expression in prostate cancer cells on the NF-κB signaling pathway." (PMID 41563982, 2026). "RIPK2 plays a vital role in the progression of various tumors, including prostate cancer." (PMID 41563982, 2026).
prostate carcinoma (continued). "RIPK2 knockout reduces prostate cancer invasion and metastasis significantly." (PMID 40406369, 2025). "However, the involvement of RIPK2 in prostate cancer chemoresistance and its association with P-gp has not yet been reported." (PMID 41563982, 2026). "Thus, RIPK2 and its downstream signaling targets may serve as therapeutic targets for chemoresistant prostate cancers." (PMID 41563982, 2026). "However, whether RIPK2 mediates chemoresistance in prostate cancer remains unclear." (PMID 41563982, 2026).
viral infection (6 papers, 2015 to 2022). "Research on influenza A virus showed that knockout of RIPK2 caused increased mortality after virus infection and indicated that RIPK2 protects the host against severe influenza A virus infection." (PMID 36733771, 2022). "N-terminal cleavage products appeared 24 h after infection showing that RIPK1 and RIPK2 are cleaved during virus infection." (PMID 26297639, 2015). "Whereas the role of RIPK2 in defense to bacterial infection is well established, evidence for RIPK2 function in response to viral infection is just beginning to emerge." (PMID 26297639, 2015). "Interestingly, in response to various stimuli including viral infections, RIPK2 potently activates NF-κB and induces apoptotic cell death as a host defense mechanism." (PMID 30456659, 2019). "The importance of RIPKs in combating viral infections is further highlighted by the fact that both RIPK1 and RIPK2 are known ISGs." (PMID 26297639, 2015).
colon cancer (5 papers, 2019 to 2022). "A recent study had shown a pro‐inflammatory microenvironment in the intestines of both NOD2‐deficient and RIPK2‐deficient increased susceptibility to colon cancer." (PMID 34268854, 2021). "Higher RIPK2 expression was observed in 16 (59.2%) patients with colon cancer and 11 (40.7%) patients with rectal cancer (p = 0.08)." (PMID 34356990, 2021). "Only HSP90AB1, RIPK2, DDX21, UCHL5, GTPBP4, and PCID2 were significantly different in UC and COAD tissues, and they all showed overexpression in colon cancer tissues compared to UC tissues." (PMID 35372018, 2022).